NLRP3 (NLR family pyrin domain containing 3)
Diseases named in the same sentence as NLRP3 in open-access papers (continued):
Sharing a sentence is not in itself a finding about the gene and the disease.
infection (continued). "While this finding indirectly suggested an involvement of NLRP3 in mediating innate immune response against a flaviviral species, there is no existing literature directly implicating the role of inflammasome in their infection." (PMID 22393394, 2012). "To examine whether the elevation of [Ca2+]cyt by the EMCV 2B protein plays a role in NLRP3 inflammasome activation, we first measured the kinetic changes in the [Ca2+]cyt after infection with EMCV by using a calcium-dependent fluorescent probe." (PMID 22916014, 2012). "It is conceivable that this inflammasome-independent production of IL-18 may be sufficient to provide some level of protection to Asc-/- and Nlrp3-/- mice against infection with low B. pseudomallei CFU." (PMID 22241982, 2011). "Using bone marrow chimeric mouse models, we show that, in contrast to NLRP3 which limits the severity of infection when present in either the hematopoietic or stromal compartments, NLRC4 plays an important role in limiting mucosal candidiasis when functioning at the level of the mucosal stroma." (PMID 22174673, 2011). "However, in those infection models NLRP3 and NLRC4 appeared to play redundant roles while in our model we were able to assign distinct functions to each inflammasome." (PMID 22241982, 2011). "Thus, adenovirus DNA introduced by infection of macrophages by virus activates the inflammasome by a NLRP3- and ASC-dependent process." (PMID 20955240, 2011). "We posit that this pattern likely reflects the fact that the NLRC4 inflammasome responds to T3SS deployment, which occurs early in the infection cycle, while activation of NLRP3 may require escape from the phagosome, which is a relatively slower event." (PMID 22241982, 2011). "Since some of these toxins exert differential cytolytic activity based on cell type, the ability to activate NLRP3-mediated signaling may be important in establishing infection in a variety of infection sites." (PMID 19826485, 2009). "Importantly, the 1918 virus up-regulated key components of the inflammasome, NLRP3 and IL-1β, whereas these genes were down-regulated by A/Vietnam/1203/04 early after infection." (PMID 19798428, 2009). "While NLRP3 promotes infection-induced osteoclastogenesis via IL-1β signaling, under sterile conditions it may restrict excessive osteoclast differentiation by inducing pyroptosis in osteoclast precursors—indicating a potential homeostatic function in physiological bone remodeling." (PMID 41596738, 2026). "However, its role in host defense against infections through NLRP3 inflammasome modulation remains unclear." (PMID 40572155, 2025). "Key pathway inhibitors—including MCC950 (targeting the NLRP3 inflammasome) and VX-765 (a caspase-1 inhibitor)—have shown therapeutic potential in animal models but are limited by suboptimal pharmacokinetics, poor tissue specificity, and risks of immunosuppression and infection during long-term use." (PMID 40832143, 2025). "Additionally, we evaluated cytokine production and NLRP3 expression in this infection model." (PMID 40142455, 2025). "Although Nlrp3 inhibition led to increased macrophage numbers in homeostasis and at early infection timepoints, it did not prevent ST-induced macrophage loss at 3 and 6 hpi, indicating that Nlrp3 is involved in regulating macrophage homeostasis but not their killing during infection." (PMID 41360763, 2025). "While infection with A. baumannii increased the expression of inflammasome-related genes, such as Nlrp3 (about 1.1) and Il1β (about 0.8) in the lungs of previously healthy mice, the transcript levels of these genes were lower in the two-hit mice (about 0.7 for Nlrp3 gene and about 0.6 for Il1β)." (PMID 40202049, 2025). "The pyroptosis-related genes NLRP3 and IL-1β were also significantly upregulated in response to infection, indicating the activation of inflammasomes and the subsequent release of pro-inflammatory cytokines that are crucial for the host’s defense against infection." (PMID 40727705, 2025).
infection (continued). "The molecular mechanism by which NLRC4 inhibits NLRP3 inflammasome activity remains unknown, but clinical evidence confirms that a certain NLRC4 polymorphism is associated with increased risk of fungal colonization in cystic fibrosis patients and infection." (PMID 41249509, 2025). "Indeed, mice lacking both AIM2 and NLRP3 were highly susceptible to infection and failed to control hyphal growth compared to either WT animals or rodents lacking a single inflammasome." (PMID 41249509, 2025). "In addition, pathways that trigger inflammation secondary to infection, such as the NLRP3 pathway, may also be activated." (PMID 40666186, 2025). "Thus, the importance of a dynamic macrophage peritoneal recruitment to acquire PDL2 expression promoting T. crassiceps successful infection, might largely be supported by NLRP3 activity." (PMID 38842647, 2024). "Notably, the levels of activated caspase-1 and released IL-1β in response to LPS and ATP, which activate the NLRP3 inflammasome; dsDNA transfection and infection with F. novicida, both as activators of the AIM2 inflammasome, were reduced following transfection with Ncf1, Ncf2, or Ncf4 siRNAs." (PMID 38886341, 2024). "After poly(I:C) infection, there was a downregulation of Uchl1 expression, while the expression of Tlr3, Caspase3, Caspase12, NOD-like receptor thermal protein domain associated protein 3 (Nlrp3), Interleukin-1β (IL-1β), IL-6, and Tumor necrosis factor alpha (Tnfα) was significantly upregulated." (PMID 38300431, 2024). "Therefore, both in resting cells and after inflammatory-associated infection clearance, PYD might selectively interact directly with human NLRP3 Ser-5 (Ser-3 in mouse NLRP3) and repress NLRP3 inflammasome activation." (PMID 38644450, 2024). "Furthermore, whether NLRP3 inflammasome assembling is required during in vivo infection with T. crassiceps must properly be studied, since we found that both IL-1β and IL-18 are differentially released during T. crassiceps infection." (PMID 38842647, 2024). "Finally, we decided to perform R20291 and R20291 ΔcdtB infections in C57BL/6J Nlrp3-/- mice." (PMID 39298531, 2024). "Therefore, we hypothesized that the transcriptional modulation of NLRP3 in the first three hours of infection is essential for subsequent IL-1β activation by the NLRP3 inflammasome." (PMID 38248981, 2024). "Our study serves as a proof of concept model identifying aggregated C protein as a possible novel agonist for NLRP3 inflammasome activation and IL-1β secretion during Hendra virus infection that may contribute to increased detrimental inflammation during in vivo infection." (PMID 37950278, 2023). "Finally, we demonstrate SARS-CoV-2 infected hACE2 mice treated orally post-infection with the NLRP3 inhibitory drug MCC950, have significantly reduced microglial inflammasome activation, and increased survival in comparison with untreated SARS-CoV-2 infected mice." (PMID 36316366, 2023). "As a protein complex composed of NLRP3, ASC, and caspase-1, NLRP3 inflammasome has the function of recognizing external stimuli and internal danger signals and initiating an inflammatory response, playing an important role in the induction of infection and autoimmune responses." (PMID 36691639, 2023). "Eventually, the inflammation caused by the release of Interleukins 1–6-32–34, TNF alpha, etc., and activation of multiple intracellular pathways (through CD-147 and NLRP3 inflammasome, etc.), may lead to rapid unstable plaque formation even after resolution of the infection." (PMID 36829118, 2023). "Thus, SARS-CoV-2 can cause an infection pool of HSPCs without requiring any other factors, and pathological triggers of the Nlrp3 inflammasome can cause a cytokine storm and pyroptosis of HSCs." (PMID 37158893, 2023). "Finally, it will be important to consider how additional intracellular signals triggered by PAO1 infection of neutrophils might contribute to NLRP3 activation." (PMID 37730693, 2023).
infection (continued). "Since our results showed that L. braziliensis exosome stimulation followed by infection induced high levels of IL-1β secretion by human macrophages, we decided to investigate whether NLRP3 activation is required to drive IL-1β production upon L. braziliensis infection in a murine model." (PMID 37841240, 2023). "NLRP3 inflammasome is a major member of the inflammasome family, which can be activated by bacterial toxins, ATP, reactive oxygen species, urea crystals and other pathogens and danger signal molecules in vivo; it is an important factor in anti-infection immunity and inducing inflammatory diseases." (PMID 36903391, 2023). "Interestingly, inhibition of NLRP3 at late stages of infection reduced IAV infection severity." (PMID 36845112, 2023). "Since the NLRP3 inflammasome is activated by various PAMPs and DAMPs, such as pathogen infection and its components, bacterial toxin, ATP, silica crystals, etc., we further examined if ODZ could inhibit the release of IL-1β from primary mouse macrophages triggered with various stimuli." (PMID 37047051, 2023). "Consequently, partial inhibition of NLRP3, or inhibition of NLRP3 in targeted cell types during infection could retain NLRP3’s protective effects while dampening detrimental inflammation." (PMID 37950278, 2023). "Furthermore, recent studies have shown that infection by picornaviruses such as rhinovirus, coxsackievirus B3 (CVB3), poliovirus, and EV-A71 results in IL-1β secretion and is also associated with the activation of the NLRP3 inflammasome." (PMID 36503883, 2022). "We investigated whether infection with the P. aeruginosa strain, PAO1, induced expression of components of the NLRP3 inflammasome and found that a 6-h infection significantly increased expression of NLRP3, the adapter protein ASC, caspase-1, IL-1β, and IL-18 in BEAS-2B bronchial epithelial cells." (PMID 35215060, 2022). "As expected, AIM2 deficiency sharply reduced IL-1β secretion and NLRP3 deficiency could not abolish IL-1β secretion upon infection of the mutant strain." (PMID 36128739, 2022). "Therefore, NLRP3 seems to be the major receptor driving cell death (pyroptosis) during infection." (PMID 36298668, 2022). "Thus, the Sars-Cov-2 E protein may initially suppress the host NLRP3 inflammasome response to viral RNA while potentially increasing NLRP3 inflammasome responses in the later stages of infection." (PMID 34952919, 2021). "In senescence-related susceptible individuals exposed to endogenous (genetics and epigenetics) stress and exogenous (environment and infection) injury, virus-induced NLRP3 inflammasome activation may drive the inflammation response by activating caspase-1 and production of mature IL-1β and IL-18." (PMID 34638790, 2021). "Interestingly, DHA was found to inactivate nucleotide-binding domain and leucine-rich repeat containing protein-3 (NLRP3) inflammasome which is assembled in response to infection or danger signals and subsequently activates the maturation and release of many pro-inflammatory cytokines." (PMID 33399183, 2021). "The caspase-11 (CASP11)-nucleotide-binding oligomerization domain-like receptor pyrin domain-containing 3 (NLRP3) inflammasome is activated by cytosolic lipopolysaccharide, a gram-negative bacterial cell wall component, to trigger pyroptosis and host defense during infection." (PMID 34740613, 2021). "However, DDX3X deficiency did not restore NLRP3 activation after IAV–ΔNS1 infection, and we instead observed that CASP1 cleavage was reduced in Ddx3xfl/flLysMCre BMDMs compared with Ddx3xfl/fl BMDMs when infected with IAV." (PMID 33766561, 2021). "NLRP3 can also sense S. Tm infection, although the specific ligand(s) detected remains unknown." (PMID 31953493, 2020). "Indeed, both models of susceptibility are compatible; it may be that both over- and under-activity of NLRP3 engender symptomatic infection depending on the activity of other components of the immune response." (PMID 32185141, 2020).
infection (continued). "Similarly, resistance to infection and limitation of L. amazonensis replication in macrophages resulted from Dectin-1/kinase Syk activation and ROS production, which led to activation of NLRP3 inflammasome." (PMID 31961876, 2020). "Moreover, prior research suggests that some variants of virulence factors found in P. gingivalis, such as LPS and fimbriae are recognized by toll-like receptors (TLRs) during infection, subsequently triggering the NF-κB pathway to up-regulate expression of pro-IL-1β and some NLRs, like NLRP3." (PMID 32903638, 2020). "Together with long time courses of infection, these factors could contribute to why caspase-1 inhibitors are less efficient than NLRP3 inhibition in preventing primary cell death, which is consistent with previous reports of caspase-independent cell death during Mtb infection." (PMID 32385301, 2020). "However, IL-1β release induced by 212 infection was comparable in wildtype and Nlrp3−/− iBMDMs." (PMID 32111888, 2020). "Notably, HSV-1-infected NLRP3-/- mice began to die at 5 days post-infection and all infected mice died at 7 days post-infection, while infected WT mice began to die at 7 days post-infection and 30% WT mice was survival after 11 days post-infection." (PMID 32187211, 2020). "We injected MAYV at 105 or 106 PFU dose in the footpad of WT and Nlrp3-/- mice and observed that Nlrp3–/–mice had increased footpad swelling compared to WT mice at 5 days post infection with a dose of 105 PFU and at 6 days post infection with a dose of 106 PFU." (PMID 31479495, 2019). "Thus, activation of the NLRP3 inflammasome should be tightly controlled to limit microbial invasion but prevent extensive inflammatory responses that are potentially hazardous to the host during infections." (PMID 31417575, 2019). "In addition, infection of platelets with DENV leads to the assembly of the NLRP3 inflammasome, activation of caspase-1, and the production of IL-1β, which is secreted in microparticles and can promote increased vascular permeability, a phenomenon associated with the severity of the disease." (PMID 30901375, 2019). "Interestingly, in vitro, NLRP3 activation appears to be inhibited by capsulated cryptococcal cells further suggesting that PRRs may have a more important role during early infection." (PMID 29670625, 2018). "Also, by inhibiting NLRP3 expression in macrophages, AhR reduces the inflammatory response and inhibits apoptosis during infection In dendritic cells, AhR activates SFKs, which phosphorylate IDO, leading to increased enzyme activity and production of tolerogenic kynurenines." (PMID 28325761, 2017). "Consequently, infection in Nlrp3-deficient mice or treatment of WT mice with the NLRP3 inhibitor glyburide reduced C. albicans vaginitis without affecting microbial colonization." (PMID 27592079, 2016). "Furthermore, promoter region of NLRP3 gene was demethylated after Mtb H37Rv strain infection." (PMID 27366746, 2016). "Given that infection with S. typhimurium is anactivator of the NLRP3 inflammasome 37 and that S. typhimurium-mediated NLRP3 activation can beabrogated by pyruvate supplementation 34, this metabolic signature may constitute an important signal ininflammasome activation." (PMID 27508077, 2016). "However, in the Ft infection model we observed no decrease in Th2 cytokines such as IL-4 or IL-10 in Nlrp3-deficient mice at any time following infection, but IFNγ production was slightly elevated at 6 days post-infection." (PMID 27926940, 2016). "During infection, mice lacking Nlrp3 display enhanced susceptibility to various infectious agents." (PMID 27592079, 2016). "However, the role of non-NLRP3 inflammasomes during infection cannot be totally refuted." (PMID 27994587, 2016). "However, NLRP3- or NLRP6-deficiency did not compromise the ability of mice to survive an i.n. infection with F. tularensis LVS." (PMID 27779193, 2016). "However, upon challenge with a larger inoculum (150 cfu), all Nlrp3-/- mice succumbed to infection." (PMID 27926940, 2016).